U8 (U8 small nucleolar RNA )
Synonyms: LOC124900291
Gene: Small nucleolar RNA gene on chromosome 10 (5,093,408 to 5,093,543, reverse strand). Ensembl gene ENSG00000239142.
Gene Ontology:
Biological process: RNA processing
Cellular component: nucleolus
Homologues: Orthologues: chimpanzee U8 (100% identical), macaque U8 (95% identical), rabbit U8 (74% identical), mouse Gm24208 (62% identical), dog U8 (59% identical), guinea pig U8 (55% identical), mouse Gm25369 (54% identical). Paralogues in human: U8 (78% identical), U8 (71% identical), U8 (70% identical), U8 (69% identical), U8 (68% identical), U8 (66% identical), U8 (65% identical), U8 (64% identical), U8 (63% identical), U8 (60% identical), U8 (52% identical), U8 (49% identical).